DNAJB1 (DnaJ heat shock protein family (Hsp40) member B1)
Description:
Interacts with HSP70 and can stimulate its ATPase activity. Acts also with TTC1 as a chaperone adapter that regulates HSP70-dependent folding process by interacting with the HSP70 amino terminal region. Stimulates the association between HSC70 and HIP. Negatively regulates heat shock-induced HSF1 transcriptional activity during the attenuation and recovery phase period of the heat shock response. Stimulates ATP hydrolysis and the folding of unfolded proteins mediated by HSPA1A/B (in vitro).
Synonyms: HSP40; HDJ1; HSPF1; Sis1; RSPH16B
Tractability: Small molecule: a structure with a bound ligand is known; it has a binding pocket of medium quality. PROTAC: ubiquitination databases record sites on it; its protein half-life has been measured.
Gene: Protein-coding gene on chromosome 19 (14,513,789 to 14,560,391, reverse strand). Ensembl gene ENSG00000132002.
Subcellular location: Cytoplasm; Nucleus; Nucleus, nucleolus
Subcellular location (Human Protein Atlas): Nucleoplasm; Cytosol
Pathways (Reactome):
Cellular responses to stimuli: Attenuation phase; HSF1 activation; HSF1-dependent transactivation; HSP90 chaperone cycle for steroid hormone receptors (SHR) in the presence of ligand; Regulation of HSF1-mediated heat shock response
Signal Transduction: MAPK6/MAPK4 signaling
Gene Ontology:
Molecular function: ATPase activator activity; ATPase binding; cadherin binding; Hsp70 protein binding; protein binding; protein-folding chaperone binding; transcription corepressor activity; transcription regulator inhibitor activity; protein folding chaperone
Biological process: cellular response to heat; negative regulation of inclusion body assembly; negative regulation of transcription by RNA polymerase II; positive regulation of protein folding; protein folding; regulation of cellular response to heat; response to unfolded protein; forebrain development
Cellular component: cytoplasm; cytosol; extracellular exosome; nucleoplasm; nucleus; dendritic spine; glutamatergic synapse; neuronal cell body; nucleolus; postsynapse; postsynaptic density; sperm head
Genetic constraint (gnomAD): Loss-of-function variants: 14 observed, 22.97 expected, observed/expected ratio (o/e) 0.61, 90% interval 0.4 to 0.95. The synonymous counts are far from expectation, so gnomAD's model fits this gene poorly and the ratio says little. Missense variants: 517 observed, 467.84 expected, observed/expected ratio (o/e) 1.11, 90% interval 1.03 to 1.19. Synonymous variants: 262 observed, 179.49 expected, observed/expected ratio (o/e) 1.46, 90% interval 1.32 to 1.62.
Homologues: Orthologues: chimpanzee DNAJB1 (100% identical), macaque DNAJB1 (99% identical), dog DNAJB1 (98% identical), pig DNAJB1 (97% identical), guinea pig DNAJB1 (95% identical), mouse Dnajb1 (95% identical), rat Dnajb1 (80% identical), zebrafish dnajb1a (68% identical), zebrafish dnajb1b (66% identical), Caenorhabditis elegans dnj-13 (53% identical), Drosophila melanogaster CG5001 (51% identical), Drosophila melanogaster DnaJ-1 (51% identical), and 7 more. Paralogues in human: DNAJB4 (66% identical), DNAJB5 (64% identical), DNAJB13 (48% identical), DNAJB11 (32% identical), DNAJB6 (29% identical), DNAJB2 (25% identical), DNAJB7 (25% identical), DNAJB12 (24% identical), DNAJB8 (21% identical), DNAJB14 (21% identical), DNAJB9 (19% identical).
Diseases named in the same sentence as DNAJB1 in open-access papers:
DNAJB1 is named in the same sentence as 143 diseases in open-access papers, as found by Europe PMC text mining. Sharing a sentence is not in itself a finding about the gene and the disease. The quoted sentences say what the papers report.
fibrolamellar hepatocellular carcinoma (26 papers, 2018 to 2026). A distinctive type of liver cell carcinoma that arises in non-cirrhotic livers and is seen predominantly in young patients. "For example, immunotherapeutic targeting of the hallmark DNAJB1-PRKACA fusion of fibrolamellar hepatocellular carcinoma appears particularly promising based on early findings of a patient with relapse-free survival coupled to related clinical trials underway." (PMID 40086881, 2025). "In patients with fibrolamellar carcinoma, loss of myristylation and gain of Hsp70 binding by oncogenic DnaJB1-PKAcat are responsible for abolishing RIα LLPS." (PMID 35803926, 2022). "Meanwhile, several rarer hepatocellular carcinoma subtypes, which together may account for 20–30% of cases, have been defined by consistent morphomolecular and clinical features, with fibrolamellar carcinoma and its diagnostic DNAJB1–PRKACA translocation being one prime example." (PMID 31433515, 2020). "Fibrolamellar carcinoma (FLC) is a lethal liver cancer that is characterized by the DNAJB1-PRKACA (DP fusion) oncogene." (PMID 38512964, 2024). "The DNAJB1-PRKACA fusion transcript has been identified in many cases of fibrolamellar hepatocellular carcinoma." (PMID 36900206, 2023). "DNAJB1‐PRKACA fusion transcripts are considered to be oncogenic drivers of fibrolamellar hepatocellular carcinoma." (PMID 37828807, 2023). "This study reports on the identification, characterization, and immunotherapeutic application of HLA-presented neoantigens specific for the DNAJB1-PRKACA fusion transcript in fibrolamellar hepatocellular carcinoma." (PMID 36302754, 2022). "The DNAJB1-PRKACA fusion transcript is the oncogenic driver in fibrolamellar hepatocellular carcinoma, a lethal disease with limited therapeutic options." (PMID 36302754, 2022). "•A unique genetic alteration drives the pathogenesis of fibrolamellar carcinoma (DNAJB1-PRKCA fusion) and hepatic haemangioendothelioma (CAMTA1-WWTR1 fusion)." (PMID 33205035, 2021). "DNAJB1-PRKACA gene fusion is reported to play an oncogenic promoter role in fibrolamellar hepatocellular carcinoma." (PMID 32984053, 2020). "Recently, fibrolamellar carcinomas were found to harbor a characteristic somatic gene fusion, DNAJB1–PRKACA." (PMID 28862261, 2018). "The results from this study significantly extend the number of non-fibrolamellar carcinoma cases tested for DNAJB1–PRKACA fusion (N=88)." (PMID 28862261, 2018). "The results from this study demonstrate the utility of FISH as a clinical test to detect the DNAJB1–PRKACA that is found in fibrolamellar carcinomas." (PMID 28862261, 2018). "Fibrolamellar carcinoma and hepatic haemangioendothelioma are driven by unique somatic genetic alterations (DNAJB1-PRKCA and CAMTA1-WWTR1 fusions, respectively), while the pathogenesis of hepatocholangiocarcinoma remains more complex, as suggested by its histological diversity." (PMID 33205035, 2021). "The fusion of PRKACA and DNAJB1 is dominant and oncogenic in fibrolamellar hepatocellular carcinoma (FLC), while the DNAJB1-PRKACA or ATP1B1-PRKACB fusion is also detected in pancreatobiliary neoplasms." (PMID 38233872, 2024). "First, ES cannot find P/LP variants in intronic regions or poorly covered regions; second, we did not do homozygous CNV calls for ES data and might miss heterozygous CNVs or small genomic deletions, such as DNAJB1-PRKACA in fibrolamellar hepatocellular carcinoma." (PMID 38057357, 2023). "DNAJB1-PRKACA fusion was found in fibrolamellar hepatocellular carcinoma (FLC) and contributes to tumor pathogenesis." (PMID 35627126, 2022).
fibrolamellar hepatocellular carcinoma (continued). "Some of the identified pancreatic gene fusions have been reported in the context of other cancer types: One case carried a DNAJB1-PRKACA fusion, which has been described in fibrolamellar hepatocellular carcinoma." (PMID 33441414, 2021). "When part of the heat shock protein DnaJB1 is fused to the catalytic subunit of cAMP-dependent protein kinase (PKA), this fusion protein drives the development of fibrolamellar hepatocellular carcinoma." (PMID 33370777, 2020). "The DNAJB1-PRKACA fusion transcript is the oncogenic driver in fibrolamellar hepatocellular carcinoma, a lethal disease lacking specific therapies." (PMID 36302754, 2022). "A fusion gene of DNAJB1/HDJ1 and PRKACA (protein kinase cAMP-activated catalytic subunit alpha), resulting from an ~400 kb of in-frame deletion on chromosome 19, is found in nearly all cases of fibrolamellar hepatocellular carcinoma (FL-HCC)." (PMID 34948322, 2021). "In fibrolamellar hepatocellular carcinoma (FL-HCC), which is a rare liver tumor, a ~400-kilobase deletion on chromosome 19 leads to a chimeric gene product consisting of exon 1, also including parts of exon 2, of DNAJB1 fused with exon 2–10 of PRKACA (DNAJB1-PRKACA)." (PMID 30258407, 2018).
hepatocellular carcinoma (13 papers, 2014 to 2024). A malignant tumor that arises from hepatocytes. "Only one sample of fibrolamellar hepatocellular carcinoma was included in the TCGA data set that we analysed, and our study revealed that it indeed harboured the characteristic DNAJB1–PRKACA fusion." (PMID 25204415, 2014). "For example, a SEMM of fibrolamellar hepatocellular carcinoma (FL-HCC) was generated by triggering the intra-chromosomal deletion Dnajb1-Prkaca." (PMID 33968774, 2021). "Successful deletion was observed in 80% of the mice and resulted in a Dnajb1–Prkaca fusion mutation, which has been identified in 80–100% of patients with fibrolamellar hepatocellular carcinoma (FL-HCC), a rare form of liver cancer whose molecular basis is not established." (PMID 32977396, 2020). "Three HLA class I-expressing hepatocellular carcinoma (HCC) cell lines (HLE, SMMC-7721, and HepG2) were transduced with an expression construct that allowed the Doxycycline (Dox)-dependent expression of the DNAJB1-PRKACA fusion protein." (PMID 36302754, 2022).
lung carcinoma (13 papers, 2017 to 2024). "Because DNAJB1 can promote the growth of lung cancer by enhancing EGFR signaling through K48-linked ubiquitination of MIG6, modulation of DNAJB1 might provide a novel therapeutic approach." (PMID 36499297, 2022). "In lung cancer, DNAJB1 is required for epidermal growth factor receptor (EGFR) signaling activation by inducing proteasomal degradation of mitogen-inducible gene 6 (MIG6), leading to enhanced proliferation of lung cancer cells." (PMID 36499297, 2022). "We also observed associations between fusion status and expression level in well-known fusions, such as RET–NTRK1 in thyroid cancer, EML4–ALK in lung cancer, and DNAJB1–PRKACA in the FLC subtype of liver cancer." (PMID 29617662, 2018). "Studies had shown that DNAJB1 was highly expressed and might be recognized as a self‐antigen in lung cancer patients." (PMID 37828807, 2023). "Thus, targeting DNAJB1 could improve the therapeutic efficacy against gefitinib-resistant lung cancers, marking a possible advance in cancer treatment methods." (PMID 38672583, 2024).
breast carcinoma (11 papers, 2011 to 2024). "DNAJB1 binds to mitogen-inducible gene MIG6, a tumour suppressor, which positively regulates epidermal growth factor signalling, leading to breast cancer development." (PMID 32139710, 2020). "Here, we show that upregulation of DNAJB1 and HMOX1 in MCF7 breast cancer cells was time-dependent." (PMID 39138277, 2024).
liver cancer (10 papers, 2017 to 2026). An epithelial or non-epithelial malignant neoplasm that arises from the liver. "In this paper, we identified cancer cells expressing the DNAJB1-PKAc in 1–3-year-old children with pediatric liver cancers and children with biliary atresia." (PMID 39796711, 2024). "The expression of DNAJB1-PKAc enhances the development of pediatric liver cancers by bringing fibrolamellar-specific disorders, by increasing the rate of proliferation, and by increasing resistance to chemotherapy." (PMID 39796711, 2024). "Interestingly, recurrent MERTK fusions are singletons in each individual cancer type with TMEM87B, and PRKACA fusions are observed only in liver cancer with DNAJB1." (PMID 29617662, 2018).
Parkinson disease (9 papers, 2012 to 2024). A progressive degenerative disorder of the central nervous system characterized by loss of dopamine producing neurons in the substantia nigra and the presence of Lewy bodies in the substantia nigra and locus coeruleus. "This machinery, composed of the constitutive Hsp70 (Hsc70), the class B J-protein DnaJB1 and the nucleotide exchange factor Apg2 (Hsp110), disassembles amyloids of α-synuclein implicated in Parkinson’s disease as well as of other disease-associated proteins such as tau and huntingtin." (PMID 34685723, 2021). "Interestingly, a powerful disaggregase system involving Hsc70, Hsp110, and the class B J-protein DNAJB1 has recently been identified for Parkinson's related α-synuclein fibrils." (PMID 27080260, 2016). "Thus heat-shock, cigarette smoke, or chemical treatments with elesclomol or the HSP90-inhibitor geldanamycin, as well as in chronically challenged tissues in Parkinson's disease, type II, DNAJB1 and DNAJB4 were found to be systematically more over-expressed than type I, DNAJA1 and DNAJA2." (PMID 25988148, 2014).
autoimmune disease (7 papers, 2013 to 2024). A disorder resulting from loss of function or tissue destruction of an organ or multiple organs, arising from humoral or cellular immune responses of the individual to their own tissue constituents. "Similarly, in another autoimmune disease, miR-155-3p targets two genes (Dnaja2 and Dnajb1) that negatively regulated Th17 differentiation contributing to potentiate the Th17 response." (PMID 35370692, 2022). "DNAJB1 belongs to HSP40 family plays a role in inflammatory conditions and autoimmune diseases." (PMID 29618337, 2018).
Insulin resistance (6 papers, 2011 to 2025). Increased resistance towards insulin, that is, diminished effectiveness of insulin in reducing blood glucose levels. "It has been demonstrated that elevated levels of DNAJB1 are linked to insulin resistance." (PMID 40469433, 2025).
lung adenocarcinoma (5 papers, 2017 to 2025). A carcinoma that arises from the lung and is characterized by the presence of malignant glandular epithelial cells. "TPD52L2, a member of the TPD52 family, can be used to predict the prognosis of lung adenocarcinoma, and DNAJB1 is also one of the diagnostic and prognostic markers of pancreatic cancer." (PMID 36010914, 2022). "To evaluate the possibility for clinical application, we tested the expression of DNAJB1, MCU, MPRIP, PSAP, RAI14, ZNF131 and TMC5 in 71 lung adenocarcinoma samples and paired adjacent normal tissue samples (>2 cm away from the tumor) from patients who underwent lobectomy or pneumonectomy." (PMID 29285248, 2017). "Moreover, DNAJB1/HDJ1 binds to mitogen-inducible gene-6 (MIG6), a tumor suppressor that inhibits the EGFR signaling, which decreases the protein level of MIG6 by enhancing its ubiquitination, leading to upregulation of the EGFR signaling pathway in A549 lung adenocarcinoma and HCT116 CRC cell lines." (PMID 34948322, 2021).
multiple myeloma (5 papers, 2016 to 2024). "DNAJB1 downregulation has not been addressed in lymphomagenesis, whereas DNAJB1 has been reported as one of the target genes in multiple myeloma." (PMID 37705009, 2023).
pancreatic cancer (5 papers, 2020 to 2023). "In cholangiocarcinoma (CCA) and pancreatic cancer, increased DNAJB1 expression is associated with pathologically advanced cancer, tumor stage, lymph node metastasis, and clinical stage in patients." (PMID 36499297, 2022). "DNAJB1 can serve as a potential diagnostic and prognostic biomarker for pancreatic cancer." (PMID 32984053, 2020). "DNAJB1 may serve as diagnostic and prognostic biomarkers for pancreatic cancer." (PMID 32984053, 2020). "DNAJB1 has been reported to be a cancer biomarker for targeted therapy and prognosis of pancreatic cancer." (PMID 36967783, 2023). "It has been suggested that DNAJB1 has obvious novel diagnostic and prognostic implications for CCA and pancreatic cancers as an unfavorable biomarker for patient survival." (PMID 36499297, 2022). "The role of DNAJB1 in the proliferation, migration, and invasion of pancreatic cancer cells was verified in vivo and in vitro." (PMID 32984053, 2020). "The xenograft model and cellular functional experiments were used to investigate the potential role of DNAJB1 in pancreatic cancer." (PMID 32984053, 2020). "The bioinformatic analysis indicated that DNAJB1 can serve as a novel biomarker for pancreatic cancer." (PMID 32984053, 2020). "DNAJB1 knockdown significantly inhibited the proliferation, migration, and invasion of pancreatic cancer cells in vivo and in vitro." (PMID 32984053, 2020). "The analysis indicated that DNAJB1 may serve as a novel biomarker for the diagnosis and prognosis of pancreatic cancer." (PMID 32984053, 2020). "The molecular mechanisms of DNAJB1 in pancreatic cancer must be elucidated in future studies." (PMID 32984053, 2020). "The expression level of exosomal DNAJB1 was upregulated in patients with pancreatic cancer." (PMID 32984053, 2020).
gastric cancer (4 papers, 2005 to 2023). A primary or metastatic malignant neoplasm involving the stomach. "F nucleatum-induced neutrophil transcriptional activation may be implicated in gastric cancer via several candidate genes including DNAJB1, EHD1, IER2, CANX, and PH4B among the top genes of interest." (PMID 36033825, 2022). "F nucleatum-induced neutrophil transcriptional activation may be implicated in gastric cancer via several candidate genes including DNAJB1, EHD1, IER2, CANX, and PH4B." (PMID 36033825, 2022).
glioblastoma (4 papers, 2016 to 2025). The most malignant astrocytic tumor (WHO grade IV). "For example, Gli36 glioblastoma cells release DnaJB1 in small EVs, whereas DKO-1 colon cells release DnaJB1 in both small and large EVs." (PMID 36581212, 2023). "To analyze whether this also functions in a highly malignant brain tumor, we knocked down the expression of Hsp70 (HSPA1A) and its two most abundant co-chaperones, Hdj1 (DNAJB1) and Hdj2 (DNAJA1) in a C6 rat glioblastoma cell line." (PMID 26959111, 2016).
neuroblastoma (4 papers, 2009 to 2023). Neuroblastoma (NB) is the most common solid, extracranial childhood tumor. "DNAJB1 overexpresses 7- and 5-fold for neuroblastoma SH-SY5Y [SH] and differentiated SH-SY5Y [SH(D)], respectively; BAG3 at 11- and 6-fold; and HSPH1 at 2.7- and 3.2-fold." (PMID 36979108, 2023).